RELA (RELA proto-oncogene, NF-kB subunit)
Description:
NF-kappa-B is a pleiotropic transcription factor present in almost all cell types and is the endpoint of a series of signal transduction events that are initiated by a vast array of stimuli related to many biological processes such as inflammation, immunity, differentiation, cell growth, tumorigenesis and apoptosis. NF-kappa-B is a homo- or heterodimeric complex formed by the Rel-like domain-containing proteins RELA/p65, RELB, NFKB1/p105, NFKB1/p50, REL and NFKB2/p52. The heterodimeric RELA-NFKB1 complex appears to be most abundant one. The dimers bind at kappa-B sites in the DNA of their target genes and the individual dimers have distinct preferences for different kappa-B sites that they can bind with distinguishable affinity and specificity. Different dimer combinations act as transcriptional activators or repressors, respectively. The NF-kappa-B heterodimeric RELA-NFKB1 and RELA-REL complexes, for instance, function as transcriptional activators. NF-kappa-B is controlled by various mechanisms of post-translational modification and subcellular compartmentalization as well as by interactions with other cofactors or corepressors. NF-kappa-B complexes are held in the cytoplasm in an inactive state complexed with members of the NF-kappa-B inhibitor (I-kappa-B) family. In a conventional activation pathway, I-kappa-B is phosphorylated by I-kappa-B kinases (IKKs) in response to different activators, subsequently degraded thus liberating the active NF-kappa-B complex which translocates to the nucleus. The inhibitory effect of I-kappa-B on NF-kappa-B through retention in the cytoplasm is exerted primarily through the interaction with RELA. RELA shows a weak DNA-binding site which could contribute directly to DNA binding in the NF-kappa-B complex. Besides its activity as a direct transcriptional activator, it is also able to modulate promoters accessibility to transcription factors and thereby indirectly regulate gene expression. Associates with chromatin at the NF-kappa-B promoter region via association with DDX1. Essential for cytokine gene expression in T-cells. The NF-kappa-B homodimeric RELA-RELA complex appears to be involved in invasin-mediated activation of IL-8 expression. Key transcription factor regulating the IFN response during SARS-CoV-2 infection.
Synonyms: NFKB3; p65; AIF3BL3; CMCU
Tractability: Small molecule: a drug acting on it is in phase 2 or 3 trials; a structure with a bound ligand is known; a high-quality ligand is known; it belongs to a druggable protein family. PROTAC: UniProt records ubiquitination sites on it; ubiquitination databases record sites on it; its protein half-life has been measured; a small molecule that binds it is known.
Target class: Transcription factor
Chemical probes: URSOLIC ACID
Safety:
Unwanted effects reported when the protein is acted on. In parentheses: how it was acted on, where the effect was seen, and who reports it.
hepatotoxicity (source: ClinPGx)
Gene: Protein-coding gene on chromosome 11 (65,653,599 to 65,663,090, reverse strand). Ensembl gene ENSG00000173039.
Subcellular location: Nucleus; Cytoplasm
Subcellular location (Human Protein Atlas): Cytosol
Pathways (Reactome):
Immune System: Activation of NF-kappaB in B cells; CD209 (DC-SIGN) signaling; CLEC7A (Dectin-1) signaling; CLEC7A/inflammasome pathway; DEx/H-box helicases activate type I IFN and inflammatory cytokines production; Dectin-1 mediated noncanonical NF-kB signaling; Downstream TCR signaling; FCERI mediated NF-kB activation; Interleukin-1 processing; Interleukin-1 signaling; RIP-mediated NFkB activation via ZBP1; Regulation of PD-L1(CD274) transcription; TAK1-dependent IKK and NF-kappa-B activation; TRAF6 mediated NF-kB activation; The NLRP3 inflammasome
Cellular responses to stimuli: Regulation of NFE2L2 gene expression; Senescence-Associated Secretory Phenotype (SASP); Turbulent (oscillatory, disturbed) flow shear stress activates signaling by PIEZO1 and integrins in endothelial cells
Disease: IkBA variant leads to EDA-ID; Purinergic signaling in leishmaniasis infection; SARS-CoV-1 activates/modulates innate immune responses
Signal Transduction: NF-kB is activated and signals survival; Regulated proteolysis of p75NTR
Cell-Cell communication: Activation of STAT3 by cadherin engagement
Chromatin organization: PKMTs methylate histone lysines
Developmental Biology: Transcriptional regulation of white adipocyte differentiation
Gene expression (Transcription): Transcriptional Regulation by VENTX
Metabolism of proteins: SUMOylation of immune response proteins
Gene Ontology:
Molecular function: actinin binding; chromatin binding; chromatin DNA binding; DNA binding; DNA-binding transcription activator activity, RNA polymerase II-specific; DNA-binding transcription factor activity; DNA-binding transcription factor activity, RNA polymerase II-specific; DNA-binding transcription factor binding; DNA-binding transcription repressor activity, RNA polymerase II-specific; general transcription initiation factor binding; histone deacetylase binding; identical protein binding; NF-kappaB binding; peptide binding; phosphate ion binding; protein binding; protein homodimerization activity; protein kinase binding; RNA polymerase II cis-regulatory region sequence-specific DNA binding; RNA polymerase II core promoter sequence-specific DNA binding; RNA polymerase II transcription regulatory region sequence-specific DNA binding; transcription cis-regulatory region binding; transcription coactivator binding; ubiquitin protein ligase binding; ankyrin repeat binding; and 3 more
Biological process: antiviral innate immune response; canonical NF-kappaB signal transduction; cellular response to angiotensin; cellular response to hydrogen peroxide; cellular response to interleukin-1; cellular response to interleukin-6; cellular response to lipopolysaccharide; cellular response to lipoteichoic acid; cellular response to nicotine; cellular response to peptidoglycan; cellular response to tumor necrosis factor; cytokine-mediated signaling pathway; defense response to tumor cell; inflammatory response; interleukin-1-mediated signaling pathway; intracellular signal transduction; negative regulation of angiogenesis; negative regulation of apoptotic process; negative regulation of cytokine production involved in inflammatory response; negative regulation of DNA-templated transcription; negative regulation of extrinsic apoptotic signaling pathway; negative regulation of miRNA transcription; negative regulation of non-canonical NF-kappaB signal transduction; negative regulation of transcription by RNA polymerase II; neuropeptide signaling pathway; and 37 more
Cellular component: chromatin; cytoplasm; cytosol; glutamatergic synapse; NF-kappaB complex; NF-kappaB p50/p65 complex; nucleolus; nucleus; transcription regulator complex; nucleoplasm
Genetic constraint (gnomAD): Loss-of-function variants: 14 observed, 54.73 expected, observed/expected ratio (o/e) 0.26, 90% interval 0.17 to 0.4. The upper end of that interval is the gene's LOEUF score, 0.4, which puts it in group 1 of 6, group 1 being the genes least tolerant of losing a copy. Missense variants: 527 observed, 713.4 expected, observed/expected ratio (o/e) 0.74, 90% interval 0.69 to 0.79. Synonymous variants: 301 observed, 284.46 expected, observed/expected ratio (o/e) 1.06, 90% interval 0.96 to 1.16.
Homologues: Orthologues: chimpanzee RELA (99% identical), macaque RELA (98% identical), pig RELA (93% identical), dog RELA (91% identical), guinea pig RELA (91% identical), rat Rela (90% identical), mouse Rela (89% identical), tropical clawed frog rela (51% identical), zebrafish rela (42% identical), Drosophila melanogaster dl (30% identical), Drosophila melanogaster Dif (26% identical). Paralogues in human: REL (38% identical), RELB (33% identical), NFKB2 (30% identical), NFKB1 (28% identical).
Diseases named in the same sentence as RELA in open-access papers:
RELA is named in the same sentence as 338 diseases in open-access papers, as found by Europe PMC text mining. Sharing a sentence is not in itself a finding about the gene and the disease. The quoted sentences say what the papers report.
ependymoma (105 papers, 2014 to 2026). A WHO grade II, slow growing tumor of children and young adults, usually located intraventricularly. "The diagnostic category of RELA fusion‐positive ependymoma was therefore introduced in the most recent 4th edition of the WHO Classification of Tumours of the Central Nervous System." (PMID 34314101, 2021). "Here we show that the C11orf95 component of the fusion protein dictates DNA binding activity while the RELA component is required for driving the expression of ependymoma-associated genes." (PMID 32909151, 2020). "Supratentorial ependymoma are divided into two subtypes based on mutational drivers namely, C11orf95-RELA (RELA) fusions and YAP1 (YAP) fusions." (PMID 32903405, 2020). "Previous studies have demonstrated increased expression of stem cell marker nestin to be associated with poor prognosis in intracranial ependymomas, with high expression levels in RELA fusion positive ST EPNs." (PMID 30464804, 2018). "Tumors harboring C11ORF95 gene fusions to RELA accounted for more than 70% of supratentorial ependymomas (median age 8 years, range 0–69 years) and were associated with a poor prognosis with 5-year progression-free and overall survival of 29 and 75%, respectively." (PMID 27858204, 2017). "In fact, the RelA gene is a proto-oncogene that encodes the RelA subunit (also known as p65) of the NF-kappa-B (NF-κB) transcription factor, which is involved in many cellular processes and in the progression of many diseases, such as Ependymoma and Reticuloendotheliosis, and most importantly PCa." (PMID 30813391, 2019). "Our results are consistent with growing evidence of a unique immune milieu in RELA-fusion ependymomas." (PMID 41417285, 2025). "In pediatric patients, the key subtypes include posterior fossa ependymoma Group A (PF-A) and Group B (PF-B), as well as supratentorial ependymomas with RELA fusion or YAP1 fusion." (PMID 41417285, 2025). "Ependymomas with ZFTA::RELA fusion reveal cytoplasmic positivity for L1CAM and diffuse nuclear staining for p65 protein (encoded by RELA gene)." (PMID 38544524, 2024). "Gene fusions involving RELA in ependymoma activate the NF-KB transcription pathway and drive tumorigenesis." (PMID 37221626, 2023). "Ependymoma that harbored a RELA fusion (ST-RELA) had high PD-L1 expression on both the tumor cells and myeloid cells." (PMID 37509316, 2023). "PD-1 and PD-L1 expression have been observed in supratentorial ependymomas, posterior fossa ependymomas, and myeloid cells; the highest expression levels were seen in supratentorial RELA fusion–positive ependymomas." (PMID 37366884, 2023). "One pediatric patient with recurrent RELA-fusion, PD-L1+ (20%) ependymoma was treated with nivolumab and sirolimus and had stable disease for 1 year after the initiation of immunotherapy." (PMID 37366884, 2023). "Among the three samples classified historically as CNS-PNET, methylation profiling suggested the molecular diagnosis of the high-grade neuroepithelial tumor with BCOR alteration (HGNET-BCOR), ETMR, and ependymoma with RELA-fusion." (PMID 37835574, 2023). "Specifically, in RELA fusion-type ST ependymomas, there is an upregulation of N-cadherin mRNA levels, along with SNAI1/Snail, SNAI2/Slug, and ZEB1, which are genes related to the EMT and downregulation of E-cadherin." (PMID 36291193, 2022). "Supratentorial ependymomas are divided into ST ependymomas with ZFTA (former RELA-/C11orf95–fusion positive ependymomas), tumors with a YAP1-MAMLD1 fusion, or other rare fusions." (PMID 35455542, 2022).
ependymoma (continued). "Of note, RELA ependymomas have been renamed in the most recent WHO classification to ZFTA-fusion positive with the recognition that C11orf95/ZFTA fusions can occur with non-RELA partner genes, such as MAML2/3, NCOA1/2, MN1, or CTNNA2." (PMID 35745584, 2022). "RELA fusion-positive ependymoma is considered the worst prognosis category of the three molecular subgroups of supratentorial ependymoma." (PMID 35986385, 2022). "RELA fusion-positive ependymomas have become a distinct entity in the classification of ependymal tumors since 2006, and are now classified as grade II or III, depending on histopathological anaplastic features." (PMID 35986385, 2022). "Subsequently, a RELA fusion-positive (grade II or III) ependymoma subtype was included in the 2016 WHO Classification of Tumors of the CNS." (PMID 34613526, 2022). "In our present study, the majority of supratentorial ependymomas (9 out of 14) belonged to the RELA+ category, confirming previous reports of the high frequency of this molecular type." (PMID 34314101, 2021). "The subtype (ependymoma, RELA fusion-positive) was included in the identification of ependymas for the first time in the classification of CNS tumors by the WHO in 2016." (PMID 33387039, 2021). "Supratentorial (ST) ependymomas in children have two major subgroups: RELA fusion-positive (ST-EPN-RELA) ependymoma and YAP1 fusion-positive (ST-EPN-YAP1) ependymoma." (PMID 33869004, 2021). "More specifically, approximately 27 and 10% of RELAFUS1 target genes in mEPN and 293T-RELAFUS1 cells overlapped with the Rela target genes in MEFs, respectively, indicating a critical implication of RELA target genes in RELAFUS1-driven ependymoma formation." (PMID 33685520, 2021). "RELA fusion-positive supratentorial ependymomas seem to affect older children and have a poor prognosis, whereas supratentorial ependymomas displaying YAP‐1 fusions affect children below 3 years of age." (PMID 34468789, 2021). "Based on histopathology, the WHO classifies ependymomas into four subtypes: subependymoma and myxopapillary ependymoma (grade I); ependymoma (grade II); ependymoma, RELA-fusion-positive (grade II or III); and anaplastic ependymoma (grade III)." (PMID 33931704, 2021). "In contrast to RELA-fused tumors associated with adverse outcomes, YAP1-MAMLD1 fused ependymomas show an excellent prognosis." (PMID 33481105, 2021). "The current concept implies supratentorial ependymomas comprising C11orf-RELA-fused or YAP1-MAMLD1-fused ependymoma as well as subependymoma." (PMID 33481105, 2021). "They exhibited histological similarities with the RELA-fusion positive ependymoma and EMA immunohistochemistry was positive in all cases." (PMID 33481105, 2021). "The molecular groups remaining in the supratentorial compartment are the ependymomas with an RELA fusion and YAP1 fusion genes." (PMID 34203272, 2021). "Taken together, these results suggest that most RELAFUS1 target genes were actively transcribed, thereby driving specific oncogenic pathways necessary for ependymoma formation in significant collaboration with the RELA/NF-κB pathway." (PMID 33685520, 2021). "Clustering analysis of 16 supratentorial ependymomas revealed 9 tumours with a RELA fusion‐positive signature (RELA+), 1 tumour with a YAP1 fusion‐positive signature (YAP1+), and 6 not‐classified tumours." (PMID 34314101, 2021). "The cIMPACT-NOW Update 7 has replaced the WHO nosology of “ependymoma, RELA fusion positive” by “Supratentorial-ependymoma, C11orf95-fusion positive”." (PMID 34389065, 2021). "More than 70% of supratentorial ependymomas are defined by highly recurrent gene fusions in the NF-κB subunit gene RELA (ST-EPN-RELA)." (PMID 34831165, 2021). "Examination of supratentorial ependymomas, to identify RELA+ and YAP+ tumours, was based on the simultaneous analysis of nine marker genes." (PMID 34314101, 2021). "A RELA fusion-positive ependymoma is recognized as WHO II or III through the 2016 WHO classification update of CNS tumors." (PMID 34203272, 2021).
ependymoma (continued). "RELA fusion-positive subtypes account for approximately 70% of the supratentorial ependymomas found in both children and adults." (PMID 34203272, 2021). "They concluded that this suggested that in the case of RELA fusion ependymoma, the increased expression of PD-1/PD-L1 results in the exhaustion of infiltrating T-cells and immune evasion by the tumor." (PMID 32075140, 2020). "Infant ependymomas seem to fall into three biological entities, with supratentorial tumors carrying RELA or YAP fusions and PFA posterior fossa ependymomas." (PMID 32474813, 2020). "The latest WHO guideline of CNS tumor defined a RELA fusion-positive ependymoma type with extremely poor prognosis, and the expression of L1CAM was correlated well with the presence of RELA fusion." (PMID 32509846, 2020). "To reproduce the gene rearrangement giving rise to the RELAFUS1 transcript, we designed four sgRNAs (single guide RNAs) on the human C11orf95 and RELA gene loci around the breakpoints observed in human ependymomas harboring RELAFUS1." (PMID 33228790, 2020). "In this study, we have successfully shown that the endogenous RELA fusion generated through targeted gene editing was sufficient to develop ependymoma-like brain tumors in mouse brains." (PMID 33228790, 2020). "The C11orf95-RELA (RELAFUS) fusions are caused by a genomic rearrangement involving C11orf95 and RELA loci on 11q in human ependymomas." (PMID 33228790, 2020). "The presence of RELA and YAP1 fusion transcripts is the hallmark of supratentorial ependymomas, and 11q chromosomal alterations are frequently associated with complex gene rearrangements." (PMID 33228790, 2020). "The ST-EPN-RELA subgroup accounts for the majority of supratentorial ependymomas and is characterized by the presence of a gene fusion between C11orf95 and RELA gene." (PMID 33228790, 2020). "Recurrent RELA and YAP1 fusions are intimately associated with tumorigenesis in supratentorial ependymomas." (PMID 33228790, 2020). "Our findings indicate that the biological function of chromosomal alterations in RELA fusion ependymomas is essentially to create a novel splice junction, consequently resulting in an oncogenic fusion gene." (PMID 33228790, 2020). "RELA fusion-positive ependymomas are very aggressive supratentorial tumors compared to the more benign grade I or grade II ependymomas." (PMID 32613272, 2020). "RELA fusion-positive ependymoma has been considered as a novel entity according to the 2016 WHO classification of CNS tumors." (PMID 32974195, 2020). "Pediatric supratentorial ependymomas with RELA fusions (RELA-EP) have been identified as a unique novel tumor entity." (PMID 32514758, 2020). "In our series, most of the RELA fusions (17/19) occurred in intracranial ependymomas, 37.8%(17/45) of intracranial had RELA fusions, and they were related to a younger age, aggressive histopathological features." (PMID 31324163, 2019). "But only C11orf95–RELA fusions led to the development of ependymoma in a mouse model, whereas overexpression of C11orf95, or RELA or other fusions did not drive tumorigenesis in this model." (PMID 31083587, 2019). "Taken together, these data led to assume the diagnosis of RELA‐fused ependymoma (possibly with a rare alternative C11orf95‐RELA fusion transcript)." (PMID 30325077, 2019). "While interpretation of data for ABs clustering with EPN-RELA was limited by case number, observed copy number variations were compatible with findings in the reference cohort of RELA ependymomas." (PMID 30876455, 2019). "Despite recent molecular classification of ependymomas there remain only 2 documented biomarkers correlated with poor outcome, namely gain of the long arm of chromosome 16,7, and the presence of RELA driver gene fusions in a subgroup of ST ependymomas." (PMID 31311995, 2019). "RELA fusions were also significantly related to a shorter survival time in intracranial ependymomas (P < 0.001)." (PMID 31324163, 2019).